BRAF (B-Raf proto-oncogene, serine/threonine kinase)
Diseases named in the same sentence as BRAF in open-access papers (continued):
Sharing a sentence is not in itself a finding about the gene and the disease.
multiple myeloma (continued). "Here, we report the case of a patient with triple‐class refractory myeloma harboring BRAF mutation that achieved clinical response to dual BRAF and MEK inhibition but experienced early disease progression related to a clonal evolution involving RAS." (PMID 35847743, 2020). "In our cohort, 46 patients were treated with at least 1 cycle of anti-myeloma treatment and 20 of them had BRAF, KRAS and NRAS mutations." (PMID 32284750, 2020). "In general, the importance of MAP kinase signaling in PC biology is suggested by the recurrent mutations of NRAS, KRAS, and BRAF in myeloma." (PMID 30642980, 2019). "Of note, BRAF mutations (G469A, K601N, and V600E) in myeloma were discovered albeit at low frequency (7 out of 161 patients = 4%)." (PMID 29250532, 2017). "BRAF mutations (22%, 5/23) were also found in five myeloma patients including two patients with both AL amyloidosis and myeloma." (PMID 27634910, 2016). "In this study, we identified mutations in three well-known oncogenes, KRAS, NRAS, and BRAF, in multiple myeloma patients." (PMID 27634910, 2016). "There is currently an open-label, phase II study of vemurafenib in patients with BRAF V600 mutation-positive cancers which includes myeloma patients (NCT01524978)." (PMID 26137536, 2015). "Our data confirm and extend previous published evidence that MAPK pathway activation is recurrent in myeloma; the finding that it is mediated by BRAF mutations in a significant fraction of patients has potentially immediate clinical implications." (PMID 26090869, 2015). "In this retrospective study, we have analyzed biopsies from 209 patients with myeloma, 11 of whom harbor the BRAF V600E mutation." (PMID 25794135, 2015). "In this study, we analyzed the prevalence and clone size of BRAF V600E mutation in 209 patients with multiple myeloma and related the results to clinical phenotype, response and survival." (PMID 25794135, 2015). "By this integrated approach to early-stage multiple myeloma, we found that patients with BRAF V600E mutation responded very well to broad acting drugs and there was no relation to prognosis in early stage myeloma." (PMID 25794135, 2015). "The premise to perform genome analysis for BRAF mutations on 161 samples arose from an original WGS/WES study on 38 myeloma samples which revealed the mutation in one patient." (PMID 24803933, 2014). "The Basket study, open-label, phase II study of vemurafenib in patients with BRAF V600 mutation-positive cancers, including myeloma (NCT01524978) is ongoing." (PMID 24913924, 2014). "NCT01524978 is a phase I clinical trial to evaluate the effects of Vemurafenib on patients with multiple myeloma and other cancers containing the BRAF V600E mutation." (PMID 23085539, 2012). "BRAF has been observed to be mutated in 8 of 199 patients (4%) with multiple myeloma and 4 of those were mutant at BRAF V600E." (PMID 23006971, 2012). "This suggests that myeloma patients harboring BRAF mutations could exhibit distinct autophagy gene expression profiles and altered responses to therapy." (PMID 41040512, 2025). "Mutations in the BRAF gene are detected in 7% of patients with newly diagnosed myeloma." (PMID 39273371, 2024). "To explore the clinical and biological significance of RAS/BRAF mutations in patients with myeloma, we studied the association of RAS/BRAF mutations with a panel of parameters including laboratory data, cytogenetic aberrations, responses to therapy, and clinical outcome." (PMID 37212518, 2023). "However, vemurafenib as a single agent in the treatment of BRAF‐mutated myeloma patients has resulted in a low response rate and early resistance." (PMID 37212518, 2023). "In case reports, heavily pretreated BRAF V600E-mutated multiple myeloma patients experienced durable responses with either the BRAF inhibitor vemurafenib alone and vemurafenib plus the MEK inhibitor cobimetinib and served as proof-of-concept for the efficacy of BRAF inhibition in multiple myeloma." (PMID 35127532, 2021).
multiple myeloma (continued). "Multiple myeloma (MM) was characterized by frequent mutations in KRAS/NRAS/BRAF within the EGFR pathway that could induce resistance to EGFR inhibitors." (PMID 25894462, 2015). "We detected the BRAF V600E mutation in 5.3% of patients with multiple myeloma." (PMID 25794135, 2015). "This has particular clinical relevance, as myeloma patients with BRAF mutations may benefit from newly developed BRAF inhibitors, drugs which in some instances have shown marked clinical activity." (PMID 24803933, 2014). "Moreover, recent studies highlight the impact of BRAF mutations in multiple myeloma, which activate the MAPK signaling pathway and may induce compensatory autophagy activation." (PMID 41040512, 2025). "However, the prognostic relevance of mutations in genes of RAS/BRAF pathway in myeloma remain unclear with contradictory published results, especially in the era of novel therapeutic agents." (PMID 37212518, 2023). "Mutations in BRAF are linked to several clinical phenotypes, notably Noonan syndrome 1 (NS1) and multiple myeloma." (PMID 40998763, 2025). "Further study of BRAF-positive myeloma is required to understand the mechanisms of activation of the signaling pathway and determine the role of targeted drugs in treatment." (PMID 39273371, 2024). "In myeloma, the combination of BRAF and MEK co‐inhibition (vemurafenib and cobimetinib, dabrafenib and trametinib) has been reported in four patients with advanced MM and BRAF p.V600E mutation and resulted in transient partial response." (PMID 35847743, 2020). "The present case report highlights the need of innovative strategies to overcome resistance to BRAF/MEK co‐inhibition in multiple myeloma." (PMID 35847743, 2020). "Molecular mechanisms leading to resistance to BRAF inhibition in myeloma still need to be elucidated." (PMID 35847743, 2020). "Herein, we report a case of a patient with relapsed and refractory multiple myeloma who had a progression-free survival (PFS) of 8.5 months on BRAF-targeted therapy." (PMID 33381330, 2020). "BRAF alterations have been identified as a dominant driver mutation and as a biomarker for sensitivity to BRAF inhibition in HCL, ECD, and myeloma." (PMID 30583461, 2018). "P-ERK1/2/p-c-Jun pathway activation was also reported to mediate up-regulation of PD-L1 in BRAF-inhibitor-resistant myeloma." (PMID 28451792, 2017). "Mutation analysis revealed NRAS as the most commonly mutated gene (30%, 7/23) in myeloma patients followed by KRAS (26%, 6/23) and BRAF (22%, 5/23)." (PMID 27634910, 2016). "Mutation analysis of all myeloma patients including the six patients with AL amyloidosis revealed NRAS as the most commonly mutated gene (30%, 7/23), followed by KRAS (26%, 6/23) and BRAF (22%, 5/23)." (PMID 27634910, 2016).
multiple myeloma (continued). "In areas where the bone marrow was packed with CD138-positive myeloma cells, the proportion of BRAF V600E-positive cells varied substantially indicating different myeloma subclones." (PMID 25794135, 2015). "Only 10 myeloma patients with BRAF V600E have been described so far: 7 in a retrospective study and 3 case reports." (PMID 25794135, 2015). "We therefore tended to study the metabolic shift in myeloma cells with KRAS/NRAS/BRAF WT background in response to EGFR inhibition, which was expected to confer primary efficacy." (PMID 25894462, 2015). "BRAF V600E was detected by AS-PCR in bone marrow or EMD from 11 out of 209 patients (5.3%) with multiple myeloma." (PMID 25794135, 2015). "None of the patients with RAS/BRAF mutations in this cohort had MGUS or smoldering myeloma, supporting the idea that RAS pathway mutation is associated with symptomatic myeloma." (PMID 37212518, 2023). "We describe the clinicopathologic, cytogenetic, molecular features, and outcomes of 68 patients with RAS/BRAF‐mutated myeloma, and compare with 79 patients without any mutations." (PMID 37212518, 2023). "However, subsequent screening of larger cohorts of CLL and myeloma for both BRAFV600E and other BRAF hotspot mutations has identified a low incidence of predominantly subclonal V600E and non V600E BRAF mutations, usually associated with a poorer outcome." (PMID 35158965, 2022). "The BRAF/RAS impact will be assessed in an ongoing clinical trial (NCT03091257) evaluating dabrafenib and/or trametinib in patients with relapsed and/or refractory multiple myeloma patients according to their BRAF/RAS mutation." (PMID 30545397, 2018). "Taken together, genes involved in mitogen-activated protein kinase (MAPK) pathway such as NRAS, KRAS, and BRAF (RAS pathway 43%) and those in the nuclear factor (NF)-kappa B pathway (17%) are recurrently mutated in myeloma and these are likely important drivers of myelomagenesis." (PMID 29250532, 2017). "Notably, 6 of the 23 myeloma patients showed multi-site and/or multi-gene mutations in NRAS, KRAS, or BRAF, indicating compound aberrations in the Mitogen activated protein kinase (MAPK) pathway." (PMID 27634910, 2016). "Thus, the application of a targeted gene sequencing panel in myeloma patients identified mutations in mitogen activated protein kinase (MAPK) pathway-related genes (KRAS, NRAS, and BRAF)." (PMID 27634910, 2016). "By this integrated approach, we found that patients with BRAF V600E mutation responded very well to broad acting drugs and there was no relation to prognosis in early-stage myeloma." (PMID 25794135, 2015). "In multiple myeloma the mutational profile is mainly represented by translocations involving chromosome 14 and by single nucleotide mutations, frequently involving genes implicated in the mitogen activated protein kinase (MAPK) pathway, as KRAS, NRAS, and, less frequently, BRAF." (PMID 31709194, 2019). "The analysis revealed that our models identified probes associated with genes involved in pathways closely related to multiple myeloma, such as PI3K-Akt, MAPK, Wnt signaling, BRAF and RAF1 fusion signaling, and mTOR pathways." (PMID 39858113, 2025). "We report here a hybrid-capture-based Liquid Biopsy Sequencing (LB-Seq) method used to sequence all protein-coding exons of KRAS, NRAS, BRAF, EGFR and PIK3CA in 64 cfDNA specimens from 53 myeloma patients to >20,000 × median coverage." (PMID 28492226, 2017). "Our models identified probes whose respective genes are involved in pathways highly related to multiple myeloma, such as the PI3K-Akt, MAPK, JAK-STAT, and Wnt signaling pathways, the RAF/MAP kinase cascade, NF-kB-related pathways, and signaling by RAS and BRAF mutants." (PMID 39858113, 2025).
multiple myeloma (continued). "Interestingly, it has been shown that mutated forms of BRAF, NRAS, and KRAS can upregulate non-constitutive proteasome expression and reduce endoplasmic reticulum stress in multiple myeloma." (PMID 38774235, 2024).
rectal cancer (73 papers, 2006 to 2026). A primary or metastatic malignant neoplasm that affects the rectum. "In this study, we excluded rectal cancers and patients whose tumors harbored non-V600 BRAF mutations, closely reproducing the inclusion criteria of the ongoing A022004 study." (PMID 41294686, 2025). "A pathogenic RAS or BRAF alteration was found in 63.2% and 57.9% of colon and rectal cancer samples, respectively." (PMID 39865537, 2025). "A similar picture was seen in rectal cancer where 42.1% of samples were RAS/BRAF‐wt and 57.9% had a known or likely pathogenic RAS/BRAF alteration." (PMID 39865537, 2025). "Here, we present a case of 74-year-old woman with rectal cancer (pT4bN1bM0 Stage IIIc) harboring the BRAF V600E mutation." (PMID 38962037, 2024). "Rectal cancer with microsatellite instability was the least prevalent of all tumor locations in BRAF V600E-mutated CRC in this and other studies." (PMID 39464719, 2024). "A 42-year-old man was diagnosed with KRAS wild-type and BRAF D594N mutated stage III rectal carcinoma." (PMID 30923702, 2019). "In this extended study, we found BRAF V600E mutations had poorer prognosis both in colon and rectal cancer patients." (PMID 29666387, 2018). "Among 41 patients evaluated for BRAF gene status, only a single patient who received pulmonary metastasectomy from rectal cancer had BRAF mutation." (PMID 28402263, 2017). "KRAS mutations, are reported in 19 to 48% of patients with rectal cancer, whereas BRAF mutations are found in 0 to 12% of RC patients." (PMID 23617638, 2013). "Only a small number of studies have specifically addressed the mutational frequency of KRAS and BRAF in rectal carcinomas, reporting a mutational frequency of 21 to 46% for KRAS and about 4% for BRAF." (PMID 20979647, 2010). "However, in rectal cancer BRAF mutations are rare and non‐V600E mutations with a less dismal prognosis are seen more frequently." (PMID 39253758, 2024). "This may reflect the different clinical characteristics and prognosis of the BRAF V600E-mutated rectal cancer population from one aspect, and it is worthy of further exploration in the future." (PMID 39464719, 2024). "Although whether the feasibility and safety of intratumoral injection of OBP-702 in CRC patients remains to be elucidated, rectal cancers with KRAS/BRAF mutations may be potent candidate for treating with OBP-301 and OBP-702." (PMID 37972012, 2023). "We therefore investigated whether deep learning–based segmentation is feasible in predicting KRAS/NRAS/BRAF mutations of rectal cancer using MR-based radiomics." (PMID 34395262, 2021). "Additionally, identification of somatic mutations of KRAS, NRAS, and BRAF genes were performed by direct sequencing and pyrosequencing in pretreated biopsy tissues from 57 patients diagnosed for rectal cancer." (PMID 31998419, 2020). "Mutations in BRAF, including the V600E “hotspot,” are rare in rectal cancer (<1%)." (PMID 32923389, 2020). "The largest cohort study on BRAF ctDNA analysis found a BRAF mutation in only one of the 115 CRC patients using nested-PCR in serum, and a recent study in 97 locally advanced rectal cancer patients reported BRAF ctDNA mutations in the plasma of only two patients using ddPCR." (PMID 32328554, 2019).